CCND1 (cyclin D1)
Diseases named in the same sentence as CCND1 in open-access papers (continued):
Sharing a sentence is not in itself a finding about the gene and the disease.
cancer (continued). "Accumulating evidence also suggests that mutations of the CCND1 gene that result in nuclear retention and constitutive activation of CDK4/6 kinases are oncogenic drivers in cancer." (PMID 29969496, 2018). "A SNP G870A (rs9344) located on exon-4–intron boundary of CCND1 has been studied extensively in several cancer types." (PMID 30361291, 2018). "Based on the prognostic effect of the nuclear expressions of β-catenin and cyclin D1 in human malignant tumors, the expression of β-catenin and cyclin D1 were scored for their nuclear expression." (PMID 29416639, 2018). "Cyclin D1 is a cell cycle regulator involved in cancer cell proliferation and development, and its relative contribution to ccRCC has recently been evaluated in cyclin D1-silenced 786-O cells." (PMID 29938199, 2018). "The occurrence of cyclin D1 in colorectal tumors is correlated with high-grade cancer with metastases to lymph nodes and deeper invasion." (PMID 30551667, 2018). "CCND1 is another typical DJ-1-upregulated Wnt target gene in our RNA-Seq data, which has been widely reported to promote cancer cell proliferation by altering cell cycle progression." (PMID 30158634, 2018). "SHetA2 has been shown to induce G1 cell cycle arrest in normal and cancer cells, and the mechanism has been shown to involve phosphorylation, ubiquitination and proteolytic degradation of cyclin D1." (PMID 29273857, 2018). "In this review, aberrant splicing events in cancer-associated genes, namely BCL2L1, FAS, HRAS, CD44, Cyclin D1, CASP2, TMPRSS2-ERG, FGFR2, VEGF, AR and KLF6, will be discussed." (PMID 30463359, 2018). "LIGHT treatment readily results in accumulation of NIK, with concomitant increases in the levels of p52 and RelB, as well as one of p52 known targets in cancer cells, Cyclin D1." (PMID 30096845, 2018). "Cyclin D1 regulates cell cycle by controlling G1/S transition, and the upregulation of cyclin D1 contributes to multiple cancers." (PMID 29068422, 2017). "Tissue Studio (Definiens) quantitative analysis was performed on high-resolution digital images obtained using the ScanScope FL line scanner (Leica Biosystems) to determine levels of cyclin D1 expression specifically within the stroma of cancer specimens." (PMID 29137220, 2017). "Functional studies established that ectopic overexpression or down-regulation of NLRP6 inhibited cancer cell proliferation by inducing cell cycle arrest at the G1 phase via P21 and Cyclin D1 both in vitro and in vivo." (PMID 29340077, 2017). "The target genes include cell cycle-regulating genes (c-myc and cyclin-D1) and genes related to metastasis and the invasion of cancer cells." (PMID 28811522, 2017). "The levels of STAT3 have also been found to be elevated in many cancers where they stimulate cell proliferation (via cyclin D1) and induction of anti-apoptotic proteins (such as Bcl2)." (PMID 28467474, 2017). "In Rb-pathway, p16 not only mediates cell cycle progression through blocking CDK4/ cyclin D1 activity, but also show as a factor maintaining cisplatin resistance in cancer cells." (PMID 29254192, 2017). "Our discovery shows that LCA derivatives are promising future therapeutics for the treatment of cyclin D1-dependent cancers." (PMID 28343940, 2017). "C-myc and cyclin D1 are downstream of the Wnt pathway relating to the proliferation of cancer cells." (PMID 29069825, 2017). "There are many factors contributing to the overexpression of cyclin D1 in cancer, such as amplification and abnormal transcription of CCND1." (PMID 28602785, 2017). "Previous studies indicate that Cyclin D1 is an important downstream target of NF-κB that participates in the early phases of the cell cycle to regulate cell growth and plays a vital role in cancer initiation and progression." (PMID 29041983, 2017). "Overexpression or disordered regulation of CCND1 is predominantly correlated with early cancer onset, shorter cancer patient survival and increased metastases, and disrupts normal cell cycle process." (PMID 29113352, 2017).
cancer (continued). "Increased expression of cyclin D1 is an early event in cancer cells and cyclin D1 is regarded as an oncogene." (PMID 28746466, 2017). "Cyclin D1 is frequently deregulated in cancer and is a biomarker of cancer phenotypes and disease progression." (PMID 29178939, 2017). "The reduction in cyclin D1 after siANT2 treatment was also observed in other cancer cell lines, such as MDA-MB-231, SK-MEL-28, A549 and RKO cells, suggesting that ANT2 functions as an oncoprotein." (PMID 28368390, 2017). "To further investigate how sesaminol reduced cyclin D1 expression in cancer cells, we undertook the identification of sesaminol-binding proteins by chemical biology approach." (PMID 28368390, 2017). "Previous studies have reported that activation of LXR inhibits the proliferation of cancer cells through repressing cyclin D1 and increasing p21 and p27." (PMID 28969053, 2017). "Cyclin D1 acts as an oncogene in breast cancer by giving selective advantages to cancer cells, such as activation of its partner CDK4 and other cell cycle regulators for deregulating normal pathways and leading to abnormal cell cycle progression." (PMID 28152041, 2017). "Our results not only provide insights into the unique molecular basis of ANT2 but also indicate the potential of screening for ANT2-binding compounds as a platform for drug discovery against cyclin D1-overexpressing cancers." (PMID 28368390, 2017). "Cyclin D1 is considered by many investigators to be a cancer gene, which can lead to uncontrolled cell proliferation and cancer development." (PMID 28567097, 2017). "USP2a is a deubiquitinase responsible for stabilization of cyclin D1, a crucial regulator of cell-cycle progression and a proto-oncoprotein overexpressed in numerous cancer types." (PMID 28343940, 2017). "Several studies have defined the targets of miR-138 such as VIM, RhoC, Hif-1α, CCND1 and Sirt1 in cancer types other than RCC, which are often involved in cell migration, EMT, DNA damage repair, senescence." (PMID 28978010, 2017). "Because cyclin D1 degradation by many anti-cancer agents has been observed in human cancer cells, cyclin D1 degradation has been regarded as a useful treatment for anti-cancer." (PMID 28870200, 2017). "Aberrant activation of PI3K/AKT pathway can enhance cancer cell proliferation via induction of Cyclin D1 and repression of P27." (PMID 29296214, 2017). "Four potentially functional polymorphisms in CCND1 (rs1944129, rs7177, rs9344 and rs678653) were genotyped in this hospital-based case-control study, comprising of 1,488 RCC patients and 1,677 cancer-free controls in a Chinese population by the TaqMan assay." (PMID 29113352, 2017). "Cyclin D1 is also a well-established human oncogene and is important for the development and progression of several cancers." (PMID 28415588, 2017). "CCND1 was shown to be upregulated in several cancers, including breast, colon, prostate and hematopoietic malignancies." (PMID 28099942, 2017). "Inhibition of SCD1 in cancer cells leads to dephosphorylation and activation of GSK3β, which halts cell proliferation by inducing β-catenin and cyclin D1 ubiquitinylation and degradation." (PMID 29354058, 2017). "The curcuminoid showed a reduction in cancer cell proliferation by suppressing the cell cycle regulatory proteins Cyclin E, Cyclin D1 Cyclin B." (PMID 29029547, 2017). "CCND1 was a well-documented important regulator that promotes G1/S transition and functions as an oncogene involved in many cancers, including PTC." (PMID 28270228, 2017). "The expression of cyclin D1 is upregulated in various cancer cells by diverse mechanisms, such as increases in mRNA levels, the promotion of the translation by mammalian target of rapamycin complex 1 (mTORC1) signaling and the protein stabilization." (PMID 28368390, 2017). "Cyclin D1, a key regulator in G1-to-S-phase transition, is overexpressed and/or amplified in a large fraction of human cancers." (PMID 29262567, 2017).
cancer (continued). "The downregulation of cyclin D1 has the potential in the treatment of cancer, and various compounds that suppress cyclin D1 expression have been investigated." (PMID 28368390, 2017). "New functions of cyclin D1 have been identified, including the enhancement of cellular migration and invasion, angiogenesis, DNA damage repair, and the induction of chromosomal instability, which has expanded the known roles of cyclin D1 in cancers." (PMID 28415588, 2017). "Strong evidence implicates cyclin D1 overexpression as a collaborative oncogene in many types of cancers." (PMID 29137223, 2017). "The UBA7/UBE1L gene was shown to reduce cyclin D1 protein levels, and it possibly affects other pathways via increasing ISGylation, thus having a pronounced anti-proliferation effect in cancer cell lines." (PMID 29088719, 2017). "In cyclin D1-overexpressing spherical cancer cells, Smad2/3 phosphorylation and the total level of Smad4 were enhanced, as shown by Western blots and flow cytometry." (PMID 28415588, 2017). "Cyclin D1 is a key regulator of cell cycle and is often overexpressed in numerous cancer types including breast, colon, lung and head and neck." (PMID 28107179, 2017). "Cyclin D1 regulates cell cycle by controlling G1/S transition, and the duplication or up-regulation of cyclin D1 contributes to multiple cancers." (PMID 28369091, 2017). "Based upon genomic data from ESCC that have supported amplification of CCND1 as a prominent feature in these cancers, we evaluated the co-occurrence of alterations in this pathway in genomic data from TCGA." (PMID 28059068, 2017). "It has been reported that mTOR pathway regulates the transcription, translation and stability of Cyclin D1 in various types of cancer cells." (PMID 28743911, 2017). "In conclusion this study demonstrated the role played by tCho, β-catenin, and cyclin D1 in cancer cell development and proliferation." (PMID 28533512, 2017). "Our study on ECC demonstrated that OCT4 promoted survivin expression to inhibit apoptosis in cancer cells and promoted CCND1 expression and activated CDK4/6 activity to accelerate cell cycle progression." (PMID 29069758, 2017). "In particular, STAT3 participates in the initiation, development, and progression of human cancers by inducing STAT3 downstream genes that encode anti-apoptotic proteins, cell cycle regulators, and angiogenic factors such as Bcl-xl and cyclin D1." (PMID 28187727, 2017). "Studies showed that the increased expression of cyclin D1 in cancer cells resulted in an uncontrolled growth advantage." (PMID 29100306, 2017). "Cyclin Ds that contain Cyclin D1, Cyclin D2 and Cyclin D3, are closely related G1 cyclins and are of particular importance to the cancer field." (PMID 29041983, 2017). "In cancer cells, CCND1 is upregulated and activates CDK4/6, whereas Rb is deactivated, resulting in the dysregulation of the DNA-damage repair system and acceleration of the cell cycle." (PMID 28225893, 2017). "Both CD44 (Indian Blood Group molecule) and cyclin-D1 are critical for GBM cancer cell biology and lie upstream or downstream of the PI3K pathway." (PMID 28556811, 2017). "Cyclin D1 is a cell cycle regulator essential for the G0/G1 phase, and expression of Cyclin D1 correlates closely with development and prognosis of cancers." (PMID 27811372, 2016). "With these notions in mind, searching for agents that promote cyclin D1 degradation represents a promising strategy to discover novel cancer therapeutics." (PMID 28035994, 2016). "Conversely, knockdown of cyclin D1 stimulates these parameters in hepatocytes and cancer cell lines." (PMID 27351284, 2016). "To date, the RB1 pathway in human cancers has been reported to be disrupted only by loss of expression of CDKN2A or RB1, as well as by CDK4/CCND1 over- expression, even though SWI/SNF is known to be an essential cofactor for RB1 function." (PMID 28105458, 2016).
cancer (continued). "Overexpression of CCND1 can trigger cancer by activating many pathways, including Wnt/β-catenin signaling pathway and has been shown to exhibit oncogenic property, making it a potential therapeutic target." (PMID 27766950, 2016). "Cyclin D1 is also a well-established human oncogene because the amplification and overexpression of Cyclin D1 are involved in many kinds of cancers." (PMID 27929439, 2016). "Cyclin D1 overexpression is also found to enhance cancer cells′ resistance to chemotherapeutic agents." (PMID 27854312, 2016). "More interestingly, increased membranous-cytoplasmic Ccnd1 expression was seen in peripheral cells in comparison with inner cells, whenever cancer cells infiltrate the stroma as large cell masses (collective or pushing patterns)." (PMID 27105504, 2016). "Another important experiment indicated that upregulation of HOXA1 activated the transcription of cyclin D1 and promoted the G1-S transition in cancer cells." (PMID 26791264, 2016). "Our data indicate that in PCa, such as in other cancers of epithelial origin, RT induces cell death by promoting DNA-DSBs phenomena; in this scenario cyclin D1 seems to be the guardian against RT-induced DNA damages." (PMID 26689991, 2016). "Upregulation of CCND1 was uncovered in various cancers, indicating its potential effects on tumorigenesis process, providing a therapeutic target of this patient." (PMID 27602771, 2016). "Expression of Slug was positively correlated with that of cyclin D1 in various cancer cell lines, whereas expression of other EMT-inducing transcription factors was not." (PMID 27385093, 2016). "In mechanistic cell studies, coffee polyphenols change the expression of STAT5B and ATF-2 modifying cyclin D1 levels in cancer cells." (PMID 27608040, 2016). "CCND1 overexpression is a common event in cancer, and is usually a result of defective regulation at the post-translational level." (PMID 26799586, 2016). "Several studies reported BRG1 promotes cancer cell proliferation by cooperation with CBP or regulating cyclin D1 and cyclin E expression." (PMID 27852072, 2016). "Cyclin D1 down-regulates the expression of numerous PPARα target genes and inhibits fatty acid (FA) oxidation in both hepatic cells and in a variety of cancer cell lines." (PMID 27351284, 2016). "The HH pathway contributes to cell proliferation in development and cancer and can interact directly with the cell cycle machinery via upregulation of Cyclin D1, which regulates progression from G1 to S phase." (PMID 27893742, 2016). "CCND1 is activated in many cancers; this has prompted much focus on the development of anti- CCND1-based therapy." (PMID 26799586, 2016). "To further examine this correlation, we interrogated CCLE data (Novartis/Broad, Nature 2012) for the mRNA expression levels of Slug vs. cyclin D1 or c-Jun in various cancer cell lines (n = 967)." (PMID 27385093, 2016). "Leptin-induced effects in cancer are linked to the activation of JAK/STAT signaling pathway, which is involved in the upregulation of Cyclin D1 and proliferation of cancer cells." (PMID 27472371, 2016). "Considering the labile nature of cyclin D1 protein, it is noteworthy that cyclin D1 accumulation in many human cancers is primarily attributed to impaired cyclin D1 degradation." (PMID 28035994, 2016). "While cyclin D1:CDK4/6 complexes have a central role in regulating the initiation of the cell cycle, activating mutations in CDK4/6 are exceedingly rare in cancer." (PMID 26857361, 2016). "Inhibition of cancer cell proliferation by reduction of Cyclin D1 expression and up-regulation of p21, an inhibitor of cell cycle progression, has been shown e.g. for the structural related triterpenoid nomilin." (PMID 27518192, 2016).
cancer (continued). "PDAC, on the other hand, show aberrant and increased expression of cyclin D1 in 70-80 % of cases and cyclin D1 is functionally active and relevant for cancer growth and proliferation." (PMID 27539223, 2016). "pRB is often described as a component of a regulatory pathway that is inactivated in most cancers (the INK4A/Cyclin D1/pRB/E2F pathway)." (PMID 27401552, 2016). "In the identified pan-cancer FFLs, CCND1 and JUN are drug targets of ATO, which span three pan-cancer FFLs." (PMID 26655252, 2016). "Our analysis of various cancer cell lines from CCLE data demonstrated that expression of Slug was significantly positively correlated with that of cyclin D1, whereas expression of other EMT-inducing transcription factors was not." (PMID 27385093, 2016). "Previous studies reported a correlation between cyclin D1 overexpression, perturbation of the DNA repair machinery and acquisition of a radioresistant phenotype in cancer cells." (PMID 26689991, 2016). "In recent years, research has shown that AEG-1 is a downstream molecule of Ha-ras and cyclin D1, which can activate the PI3K-Akt, NF-κB and Wnt signaling pathways, which are closely associated with autophagy in cancer cells." (PMID 26909607, 2016). "Leptin-induced activation of STAT3 regulates several genes involved in cancer, which include cyclin D1, cyclooxygenase (COX)-2, VEGF, human telomerase reverse transcriptase (hTERT), Survivin and leptin." (PMID 27472371, 2016). "In this work, we show that Ccnd1 displays an asymmetric pattern of localization in different cancers, being more cytoplasmic and membranous in the peripheral and invasive regions of the neoplastic tissues." (PMID 27105504, 2016). "This is partially ascribed to the action of β-catenin, together with its downstream genes, c-Myc and cyclin D1, which mediate the upregulation of self-renewal and maintenance of cancer stem/progenitor cells against sublethal or lethal stimuli." (PMID 27014877, 2016). "Down-regulation of cyclin D1 has been reported to play a role in G1 cell-cycle arrest in other cancer cell lines." (PMID 26675259, 2016). "A previous report has suggested that Rac1 contributes to cancer cell proliferation via cyclin D1 induction." (PMID 26910843, 2016). "We then proceeded to correlate gene copy number with gene expression at 11q13.3 using CCND1 which is common to both NanoString PanCancer expression and cancer copy number panels." (PMID 27078887, 2016). "Cyclin D1, a protein required for progression through the G1 phase of the cell cycle, has been found to be overproduced in some cancer cells." (PMID 27070592, 2016). "The product of CCND1, cyclin D1, provide growth advantage to cancer cells and contribute toward resistance to endocrine therapy in ER-positive cancers." (PMID 27765917, 2016). "Studies showed that increased cyclin D1 expression in cancer cells resulted in an uncontrolled growth advantage." (PMID 27863410, 2016). "We made a structural attempt to study possible binding of two natural famed ligands with the potential therapeutic drug target, Cyclin D1 for cancer therapeutics." (PMID 27766950, 2016). "As the regulatory subunits of CDK4 or CDK6, CCND1 and CCND2 are required for cell cycle G1/S transition, and thus have been implicated as proto-oncogenes and attractive targets for cancer therapy." (PMID 27494902, 2016). "Disruption of Cyclin D1 proteolysis is one of the major mechanisms that cancer cells accumulate Cyclin D1." (PMID 27854312, 2016). "We also observed that BP3B inhibited cancer cell proliferation by down-regulation of Cyclin D1 and induction of p27 proteins." (PMID 27863496, 2016).